ASPG (asparaginase)
Diseases named in the same sentence as ASPG in open-access papers (continued):
Sharing a sentence is not in itself a finding about the gene and the disease.
pancreatitis (continued). "In addition to asparaginase, other chemotherapeutic agents have also been indicated in the literature as possible causes for inducing pancreatitis." (PMID 26872431, 2016). "However, asparaginase is associated with various toxicities, including hypersensitivity, pancreatitis, hyperlipidaemia, hepatotoxicity, thrombosis, and osteonecrosis, which may lead to the discontinuation of asparaginase therapy." (PMID 39439952, 2024). "Pancreatitis events occurred more in the 0–18 years age group for asparaginase, carglumic acid, clofarabine, and vincristine." (PMID 40308779, 2025). "In future study, we intend to investigate the possibility of targeting Gremlin‐1 to prevent L‐asparaginase resistance and asparaginase‐induced pancreatitis." (PMID 40285538, 2025). "Despite its effectiveness, asparaginase has notable toxicities, including hepatotoxicity, thrombosis, immunosuppression, and pancreatitis." (PMID 38539506, 2024). "Allergic reactions and silent inactivation were more common in children treated with native E. colil-Asparaginase, while pancreatitis was more common in children treated with the pegylated form." (PMID 38535043, 2024). "Obese children with ALL are likely to be at higher risk for treatment-related toxicities, such as steroid-induced hyperglycemia, asparaginase-induced pancreatitis, hepatic steatosis and osteonecrosis." (PMID 38709714, 2024). "Previous studies have indicated that severe pancreatitis is the main reason for asparaginase interruption." (PMID 39439952, 2024). "Adverse effects related to asparaginase therapy are hypersensitivity reactions, hepatotoxicity, hypertriglyceridemia, hyperglycemia, pancreatitis, encephalopathies, and thrombotic or bleeding complications." (PMID 38817959, 2023). "While hypersensitivity, pancreatitis, coagulopathy, and hepatotoxicity are of the utmost importance, asparaginase treatment has other notable toxicities." (PMID 35844739, 2022). "Historically due to the severity of initial pancreatitis, and potential for reoccurrence with additional exposure, rechallenging with further asparaginase therapy has been avoided." (PMID 35844739, 2022). "Pancreatitis is an additional asparaginase toxicity that often carries drastic consequences for patients with an estimated associated mortality of 2%." (PMID 35844739, 2022). "Patients aged 10 to 18 years were more likely to experience asparaginase-related pancreatitis than those younger than 10 years." (PMID 35958817, 2022). "We had cases of pancreatitis (n = 2), severe liver failure (n = 1), thrombosis (n = 1), and diabetes (n = 1) after treatment with asparaginase." (PMID 34622870, 2021). "We recommend a close monitoring of blood glucose levels for hyperglycemia as well as a high index of clinical suspicion for pancreatitis in patients with ALL receiving L-asparaginase." (PMID 32423425, 2020). "Recently, eight studies investigated four asparaginase-induced toxicities (hypersensitivity, pancreatitis, thrombosis, and hepatotoxicity)." (PMID 32848787, 2020). "Toxicities, like hypersensitivity, pancreatitis, coagulation abnormalities, encephalopathy, and liver dysfunction, were reported to be related to asparaginase treatment." (PMID 30832275, 2019). "Further study of asparaginase action pathway genes revealed that the 3R3R ASNS genotype was correlated with pancreatitis and allergies in ALL patients." (PMID 30832275, 2019). "The mechanism by which asparaginase induces pancreatitis is fundamentally different from its therapeutic action on the lymphoblastic cells in ALL." (PMID 27377732, 2016). "Asparaginase-related toxic events, including pancreatitis, transaminitis, hyperbilirubinemia, hypoalbuminemia, hyperglycemia, hypertriglyceridemia, hypofibrinogenemia and deep vein thrombosis (DVT), were comparable and without statistical differences." (PMID 28000713, 2016).
pancreatitis (continued). "Like other pancreatitis-inducing agents, asparaginase evoked intracellular Ca2+ release followed by Ca2+ entry and also substantially reduced Ca2+ extrusion because of decreased intracellular ATP levels." (PMID 27377732, 2016). "Effects of asparaginase-induced hypertriglyceridemia range from asymptomatic to transaminasemia, pancreatitis, and life-threatening thrombosis or hyperviscosity syndrome." (PMID 25405049, 2014). "Garbage bins should have lids, and garbage should not be stored for more than 2 h” (K1) at 98.13%, and “Children undergoing asparaginase treatment should be cautious about the occurrence of severe pancreatitis and maintain a light diet, avoiding high-fat and oily foods” (K10) at 97.51%." (PMID 39655255, 2024). "The origin, formulation, dosage, or method of administration of asparaginase do not determine the risk of pancreatitis." (PMID 39011188, 2024). "For example, ponatinib and asparaginase have overlapping toxicities (e.g., pancreatitis and hepatotoxicity) which may preclude concurrent use of these drugs." (PMID 36707619, 2023). "Therefore, we switched to asparaginase Erwinia at a dose of 10,000 IU/m2 twice weekly after the pancreatitis was under control." (PMID 34160436, 2021). "During the third asparaginase Erwinia dose, a mild pancreatitis recurred." (PMID 34160436, 2021). "These insights also provide the first pointers to rational therapies that may prevent the currently necessary cessation of asparaginase treatment of ALL in cases of severe pancreatitis." (PMID 27377732, 2016). "Existing medical conditions may contraindicate the use of peg asparaginase, including active DIC, active DVT, relevant bleeding, CNS thrombosis/bleeding, pre‐ existing pancreatitis, severe pancreatitis with prior asparaginase, and previous severe liver toxicity or disease." (PMID 38083985, 2024). "Pancreatitis may cause the early termination of asparaginase treatment without a possible change of type of asparaginase formulation." (PMID 34431241, 2022). "Some studies have found a higher risk of pancreatitis and thromboembolism, but not hypersensitivity, in adolescents than in children <10 years, while other studies have reported similar rates of asparaginase-associated toxicity in AYA patients and those <16 years of age." (PMID 34640436, 2021). "The major adverse events of asparaginase products, reported from clinical trials involving patients with ALL, include anaphylaxis and serious allergic reactions, thrombosis, pancreatitis, glucose intolerance, coagulopathy, and hepatotoxicity." (PMID 27064021, 2016). "They found that further asparaginase therapy did not trigger pancreatitis recurrence, suggesting a broader consideration of the criteria for re-exposure to asparaginase after the first AAP episode." (PMID 39439952, 2024). "The patients who had mild forms of pancreatitis resumed asparaginase, and the pancreatitis did not recur." (PMID 34640436, 2021). "Our clinical approach has been to re-introduce ASNase in patients who experienced relatively mild to moderate AAP, patients who developed pancreatic necrosis or pseudocysts during their initial episode of pancreatitis, were not eligible for asparaginase re-challenge." (PMID 40641923, 2025). "However, there is no report any side effects of asparaginase including hypercoagulable state, coagulopathy, pancreatitis, and hyperbilirubinemia." (PMID 34711008, 2021). "However, genetic screening for pancreatitis-causing genes in ALL patients is not currently standard practice, which limits our understanding of the impact of specific genetic variants on the development of AAP in pediatric ALL receiving asparaginase therapy." (PMID 39564382, 2024).
Allergy (18 papers, 2016 to 2025). An allergy is an immune response or reaction to substances that are usually not harmful. "Previous genomic association studies by us and others have found that strong risk factors for asparaginase allergy include variants within genes regulating T-cell immune response, and that this is agnostic of asparaginase preparation." (PMID 36980715, 2023). "We found that a TCR repertoire that was more varied and changed more during therapy was associated with an increased risk of clinical allergy and decreased asparaginase activity later in therapy." (PMID 36980715, 2023). "The non-coding CNOT3 variant, rs73062673, was confirmed to be strongly associated with a PEG-asparaginase allergy in ALL children in the GWAS." (PMID 30832275, 2019). "Apart from overt allergy, antibodies can also cause a so-called silent inactivation, in whichl-asparaginase is neutralized subclinically." (PMID 29098074, 2016). "This could be explained by the low number of peg-asparaginase doses administered according to the risk group (SR patients = 4 doses), which might lead to completion of peg-asparaginase treatment before the full allergic reaction occurred." (PMID 38287133, 2024). "This genetic locus was previously associated with asthma and atopy and the findings strongly support the hypothesis that an asparaginase allergy and asthma share a range of genes that might cause adverse reactions." (PMID 30832275, 2019). "The reported frequency of allergic reactions ranges from 3 to 75% depending on the type, dose, route, and duration of asparaginase administration, and allergic reaction primarily occurs after the first or second dose and virtually always is associated with zero asparaginase activity." (PMID 28413626, 2017). "Clinical allergy is associated with inactivation ofl-asparaginase by antibodies." (PMID 29098074, 2016). "Clinical allergy occurred during administration of the third (n = 11/36, 30.6%), the fourth (n = 19/36, 52.8%) or the fifth (n = 6/36, 16.7%) dose of peg-asparaginase." (PMID 38287133, 2024). "Patients exhibiting clinical allergy symptoms to one formulation of asparaginase are typically switched to another product to ensure they receive the most efficacious treatment regimen as possible." (PMID 36307379, 2023). "The use of Asparaginase is limited by its side effects, most notably severe allergic reaction, acute pancreatitis, and coagulation disorders." (PMID 35328487, 2022). "If native E.coli pegylated asparaginase allergy develops, Erwinia asparaginase is indicated because of its immunological distinction and lack of cross reactivity." (PMID 34711008, 2021). "This patient had a medical history of combined medullary/CNS relapse status which coincided with clinical allergy as urticaria for the last two doses of native E.coli asparaginase on DI time." (PMID 34711008, 2021). "Erwinia asparaginase was given to 9 of 13 patients with grade III‐IV allergic reactions, and removal of asparaginase was done in the remaining four cases." (PMID 32022463, 2020). "From January 2005 to January 2013, 59 patients first received E. coli-asparaginase, and 9 patients were excluded due to allergy to E. coli-asparaginase and switched to Erwinia asparaginase." (PMID 28000713, 2016). "Following allergy to pegylatedl-asparaginase, Erwinial-asparaginase can be substituted and achieves therapeutic activity." (PMID 29098074, 2016). "The production of anti-asparaginase antibodies has been investigated by many authors, who have reported that various IgG molecules were present in serum samples of patients with asparaginase allergies." (PMID 38535043, 2024). "Besides, asparaginase in RBCs is also used in patients with PEG-asparaginase allergy (NCT03267030, phase II) and lymphoblastoma (NCT01910428, phase I) and pancreatic adenocarcinoma (NCT01523808, phase I and NCT02195180, phase II)." (PMID 39267776, 2024).
Allergy (continued). "Moreover, 100% of participants modified treatment according to results of testing, switching to Erwinia asparaginase in case of allergy." (PMID 36307379, 2023). "Also, about 90% of participants used asparaginase activity levels in decision‐making, switching from pegylated asparaginase to Erwinia asparaginase in case of allergy or silent inactivation confirmed by assessment of the therapeutic asparaginase level." (PMID 36307379, 2023). "This diversity is characterized by dissimilar and infrequent clonotypes, which we hypothesize increases the overall chance of having a clonotypic sequence that would match to the asparaginase antigen and, thus, could mediate allergy." (PMID 36980715, 2023). "If the clinical allergy is mild or doubtful or has multiple other suspected drugs to cause reaction during the same period, the asparaginase activity with or without the antibody check is also indicated." (PMID 34711008, 2021). "Patients with low asparaginase activity or allergy may benefit from switching to an alternative form of asparaginase to maintain treatment efficacy." (PMID 34711008, 2021). "Asparaginase activity and/or antibody testing is recommended for all cases especially in a relapsed patient, history of high accumulative dose of asparaginase or suspected allergic reaction." (PMID 34711008, 2021). "The original preparation was derived from Escherichia coli (and is referred to as E. coli asparaginase), but it has been abandoned by most developed countries due to its toxicity profile (particularly allergic reactions), and the adoption of its less immunogenic pegylated form (PEG-asparaginase)." (PMID 35582721, 2019). "It’s mechanism of action differs in important ways from that of asparaginase suggesting that it may be a useful agent in asparaginase-resistant disease or where asparaginase is contra-indicated (e.g. following serious allergic reaction)." (PMID 30578463, 2019). "Thus, the development of allergy to E. coli-asparaginase required a change to Erwinia asparaginase in our department." (PMID 28000713, 2016). "Thus, a small molecule drug such as TA or a TA analog may be useful against Asparaginase-resistant malignancies or in patients with Asparaginase allergies." (PMID 35095503, 2021). "A mechanism was proposed of how an allergy could develop, suggesting that inherited HLA-DRB1 variant alleles produce amino acid variations of the protein whose interaction with asparaginase epitopes is aberrant, leading to a higher frequency of asparaginase hypersensitivity." (PMID 30832275, 2019). "We note that a premedication protocol (hydrocortisone or antihistamine drugs) was used before each dose of asparaginase, even if the patient had not previously had an allergic reaction." (PMID 34640436, 2021). "Therefore, PEG-asparaginase may have the same efficacy as E. coli-asparaginase and be safely used as another choice of asparaginase in adults with standard-risk ALL given its more rapid clearance of lymphoblasts on day 14, reduced incidence of allergy, and similar long-term outcome and convenience." (PMID 28000713, 2016). "Allergy occurred in 9 patients using E. coli-asparaginase, and no patient in the PEG-asparaginase group suffered from allergies (P < 0.001)." (PMID 28000713, 2016). "Jude Total XV protocol, which uses a higher dose of asparaginase during induction (10,000 UI/m2 on Days 6, 8, 10, 12, 14, and 16) than that used in the ALL IC BFM 2002 protocol (5000 UI/m2 on Days 12, 15, 18, 21, 24, 27, 30, and 33), and reported a higher incidence of clinical allergy (41%)." (PMID 34640436, 2021). "In total, 72 patients received PEG-asparaginase, and no patients suffered from allergy." (PMID 28000713, 2016).
hypertriglyceridemia (14 papers, 2014 to 2025). A laboratory test result indicating elevated triglyceride concentration in the blood. "Among the different preparations of asparaginase, the risk of hypertriglyceridemia has been observed to be increased with PEG-asparaginase compared to L-asparaginase almost two times when given together with dexamethasone." (PMID 39011188, 2024). "Two cases are presented here to illustrate the effects of concurrent infection on asparaginase-induced hypertriglyceridemia in patients with high-risk ALL and the use of SMOFlipid infusion as a treatment option in an acute situation." (PMID 33968859, 2021). "Future prospective research should focus on monitoring pancreatic enzyme levels and lipid profiles to better understand the relationship between hypertriglyceridemia and asparaginase-induced AP." (PMID 40895695, 2025). "The combination treatment of glucocorticoids and asparaginase can alter the lipid profile, particularly in hypertriglyceridemia." (PMID 39011188, 2024). "Some cases of severe asparaginase-induced hypertriglyceridaemia have been successfully managed with plasmapheresis, which was found to be a safe and effective method for treating hypertriglyceridaemia and preventing related complications." (PMID 36009482, 2022). "Despite its benefits in the treatment of ALL, asparaginase can have many adverse effects, including hypertriglyceridemia and hypercholesterolemia." (PMID 25405049, 2014). "Asparaginase is a critical component of ALL treatment but is associated with multiple potential toxicities, including hypertriglyceridemia." (PMID 25405049, 2014). "There is no consensus on the optimal treatment for asparaginase-induced hypertriglyceridemia, besides cessation of asparaginase." (PMID 25405049, 2014). "Nine similar published cases of asparaginase-induced hypertriglyceridemia and its complications are also discussed." (PMID 25405049, 2014). "Hypertriglyceridemia was more common in children treated according to the AIEOP-BFM ALL 2009 protocol (PEG-asparaginase) than in those treated according to ALL-IC BFM 2002 (native E. coli-asparaginase) (p = 0.013)." (PMID 32992771, 2020). "In our study, both VTE and hypertriglyceridemia were more common in children treated according to the AIEOP-BFM ALL 2009 protocol (PEG-asparaginase) than in children treated according to the ALL-IC BFM 2002 protocol (native E. coli-asparaginase)." (PMID 32992771, 2020). "Asparaginase-induced hypertriglyceridemia occurs in 10–50% of children being treated for ALL." (PMID 25405049, 2014). "However, the presence of severe hypertriglyceridemia at ALL diagnosis may suggest additional pathogenic mechanisms contributing to hypertriglyceridemia besides those associated with corticosteroid and asparaginase exposure." (PMID 32992771, 2020). "Of note, some chemotherapies, such as tamoxifen and asparaginase, inhibit LPL activity but also lead to hypertriglyceridemia." (PMID 36652113, 2023). "So, hypercholesterolemia and hypertriglyceridemia seen in ALL patients are attributed to steroids and asparaginase, respectively." (PMID 25405049, 2014). "When monitoring for toxicity and making treatment decisions, it is important to determine whether hypertriglyceridemia in children undergoing ALL therapy is due to steroids, asparaginase, or both." (PMID 25405049, 2014).